ATR (ATR checkpoint kinase)
Diseases named in the same sentence as ATR in open-access papers (continued):
Sharing a sentence is not in itself a finding about the gene and the disease.
cancer (continued). "VE‐822 is a potent ATR kinase‐specific inhibitor that is currently in phase II clinical trials for cancer treatment and has been widely used in ATR studies." (PMID 33811702, 2021). "We conducted a similar multivariate regression analysis for somatic mutations, and identified 24 significant associations in five (i.e., BRCA1, BRCA2, ATM, ATR, CHEK2) genes and higher HRD (FDR < 0.05) across cancer types." (PMID 34572800, 2021). "Genome-wide KO screens performed with ATR inhibitor in several types of cancer cell lines (293A, HCT116 and MCF10A) demonstrated that RNASEH2 deficiency induces ATR inhibitor sensitivity both in vitro and in vivo." (PMID 34884583, 2021). "The inhibition of DNA repair components, including ATM, ATR, Chk1 and Chk2, markedly sensitizes cancer cells to radiation." (PMID 34587992, 2021). "Promoted RS rates in cancer cells make the ATR/CHK1/WEE1 kinases a suitable target for anticancer therapy." (PMID 33672884, 2021). "Emerging studies revealed that cancer cells with ALT were hypersensitive to the inhibition of ATR, another component of DNA damage checkpoint-activating kinases other than ATM in human cells." (PMID 34743173, 2021). "The inhibition of ATR downregulates PD-L1 in a proteasome-dependent manner, attenuates the interaction of PD-L1/PD-1, and sensitizes cancer cells to T-cell-mediated killing." (PMID 34359720, 2021). "Paradoxically, ATM and ATR are prime cancer drug targets because DDR inhibition enhances efficacy of therapeutic radiation and many chemotherapeutic agents." (PMID 33742106, 2021). "Among all serine and threonine residues in this IDR, T94 and S98 are in close proximity to the two cancer-associated mutations E95G and S96V, while S111A is a putative ATM/ATR phosphorylation site (SQ)." (PMID 34681076, 2021). "For example, ATR inhibition alleviated dsDNA break-induced PD-L1 upregulation in various cancer cell lines." (PMID 34298632, 2021). "Next, we identified prognostic gene mutations (ATR, ERBB3, KDR, and MUC6), fusions (GOPC-ROS1 and NTRK1-SH2D2A), and VEGF signaling pathway associated with cancer recurrence." (PMID 34599262, 2021). "Several preclinical studies have demonstrated the efficacy of PARP inhibitors in combination with ATR inhibitors in many BRCA-deficient, as well as ATM-deficient, cancer models." (PMID 34027408, 2021). "The activation of ATM and/or ATR contributes to treatment resistance and pathological neoangiogenesis in cancers." (PMID 34483751, 2021). "Consistently, we found that both the ATM-Chk2 and ATR-Chk1 DDR signaling pathways were strongly activated in the cinobufagin-treated cancer cells, immediately following the generation of cinobufagin-induced DSBs and replication stress." (PMID 34425836, 2021). "Following these initial studies, several structurally unrelated ATR inhibitors have been described and widely assayed in multiple preclinical models of cancers." (PMID 35008191, 2021). "Additional investigations have revealed that co-inhibition of POLH and ATR, a protein central to the replicative stress response, offers a SL approach for the treatment of a range of cancer types." (PMID 34900730, 2021). "Remarkably, two of the four ATR (D1687 and G1691) and two of the four ATM (L2005 and D2016) conserved residues are mutated in cancer." (PMID 33742106, 2021). "Those functions of ATR/CHK1 signaling pathway provide potential therapeutic targets to overcome cancer therapeutic resistance." (PMID 34474677, 2021). "ATR inhibition can further increase cGAS-positive micronuclei and cytokine production in PARPi-treated cancer cells." (PMID 34970273, 2021).
cancer (continued). "In the majority of the models tested from different cancer types, ATR-mediated responses were demonstrated to be pivotal for TMZ resistance." (PMID 34676045, 2021). "POLQ was revealed to be synthetic lethal with DNA repair genes frequently mutated in cancer (such as ATM, ATR, BRCA1/2, FANCD2, Ku70, RAD52, RAD51C, TP53BP1) and extensive efforts for the development of Polθ inhibitors are made by several companies." (PMID 34201502, 2021). "We summarize key molecular features of DNA replication and discuss how to exploit the RepStress, ATR (ataxia telangiectasia mutated and Rad 3-related) protein kinase inhibitors and SLFN11 for cancer therapy." (PMID 34572827, 2021). "In fact, several lines of evidence suggest that cancer cells require a functional ATR to withstand the intense replicative stress elicited by the cancer genes deregulation." (PMID 35008191, 2021). "Of these, several are found in genes involved in DNA damage response and double-strand DNA repair mechanisms, including MCL1, ATR, KMT2C, and CBLC, indicating genomic instability and cancer predisposition." (PMID 34299215, 2021). "One potential explanation for these observations is that compensatory ATR activity can mitigate any HRD phenotype in ATM mutant cancer." (PMID 34572943, 2021). "Inhibitors of other components of the intra-S phase and G2 phase DNA damage checkpoints, such as ATR and Wee1, are also in clinical trials for the treatment of cancer." (PMID 34372559, 2021). "Here we uncover an unexpected biphasic concentration-dependent response of ATR/Chk1 activation controlled by the levels of TopBP1 in cancer cells." (PMID 33556369, 2021). "The activation of ATM and/or ATR in cancer cells contributes to treatment resistance and is evaluated as prognostic indexes." (PMID 34483751, 2021). "To gain insights, we identify functionally important conserved residues in ATM, ATR and budding yeast Mec1ATR via cancer genome datamining and a functional genetic analysis, respectively." (PMID 33742106, 2021). "In contrast, moderate depletion of TopBP1 by shRNA in TopBP1-overexpressing cancer cells enhanced ATR/Chk1 activation and S-phase checkpoint response after replicative stress." (PMID 33556369, 2021). "Preclinical studies demonstrated that ATR inhibition can exploit synthetic lethality (eg, in cancer cells with impaired compensatory DNA damage responses through ATM loss) as monotherapy and combined with DNA-damaging drugs such as carboplatin." (PMID 32568634, 2020). "Inhibitors of ATR are currently investigated in clinical trials and appear to enable the effective elimination of certain subsets of cancer cells." (PMID 33144657, 2020). "Ataxia telangiectasia and Rad3-related protein (ATR) are a primary sensor of DNA damage, and ATR is also a promising target in cancer therapy." (PMID 32317623, 2020). "This dependence of A3A-expressing cancer cells on the ATR checkpoint offers an opportunity for targeted therapy using ATR inhibitors." (PMID 32532990, 2020). "Inhibition of ATR resulted in destabilization of PD-L1 in a proteasome-dependent manner, attenuation of the interaction of PD-L1/PD-1 and sensitization of cancer cells to T-cell mediated killing." (PMID 33224881, 2020). "Our findings reveal a key pro-resection function for ATR and define how ATR inhibitors can be used for effective manipulation of DNA end resection capacity and DNA repair outcomes in cancer cells." (PMID 32743550, 2020). "In conclusion, this study supports anti-cancer effect of ATr blockers on PCa prognosis and this should be investigated further in controlled clinical trials." (PMID 32598349, 2020).
cancer (continued). "Although cancer cells often become more dependent on ATR for survival, the precise mechanism by which ATR signaling ensures cancer cell fitness and viability remains incompletely understood." (PMID 32743550, 2020). "Recent preclinical studies have revealed that the response to DNA damages (e.g. DNA double-strand breaks, DNA single-strand breaks and base damage) upregulates PD-L1 expression in cancer cells via ATM/ATR/Chk1 kinase activation." (PMID 32246277, 2020). "Long-term ATR inhibition represents an innovative and efficient strategy to inhibit DNA end resection and manipulate DNA repair outcomes in many cancers." (PMID 32743550, 2020). "Here, we find that intrinsic ATR signaling is crucial for the ability of cancer cells to promote DNA end resection, the first step in homology-directed DNA repair." (PMID 32743550, 2020). "Rather, ATR activity becomes critical for the survival of Myc or Cyclin E deregulated cancers with oncogene-induced replication stress." (PMID 32015826, 2020). "Our results also imply a potential strategy in enhancing cancer therapies via selective moderation of cis ATR levels." (PMID 32984322, 2020). "It should be pointed out that the current ATR inhibitors used in cancer clinical trials are specific inhibitors of ATR kinase activity which is pivotal to the hallmark ATR’s DNA damage checkpoint functions in the nucleus." (PMID 32426354, 2020). "Given the roles of apoptosis in many human diseases, particularly cancer, we propose that cytoplasmic cis-ATR enables cells to evade apoptosis, thus addicting cancer cells to cis-ATR formation for survival." (PMID 32426354, 2020). "Most cancer cells exhibit intrinsically high levels of ATR activation, which has been attributed to their increased levels of replication stress caused by oncogene-induced deregulation of DNA replication." (PMID 32743550, 2020). "In models of Ras- or MYC-driven cancer, signalling through these oncogenes has been shown to lead to sensitivity to ATR inhibition." (PMID 32354033, 2020). "Given the higher reliance of cancer cells on ATR signaling, inhibition of ATR signaling has been explored as a strategy for cancer therapy." (PMID 32743550, 2020). "Loss-of-function ARID1A mutations sensitized various cancer cells towards inhibition of EZH2, PARP, ATR, HSP90 and HDAC9 (and others)." (PMID 32272809, 2020). "Because deregulated apoptosis is a key hallmark in carcinogenesis, the involvement of PP2A in the regulation suggests the importance of the phosphorylation status of cytoplasmic Ser428 of ATR in carcinogenesis and cancer treatment." (PMID 32984322, 2020). "This differential expression suggests that ATR downregulation in CAFs is due to the presence of these fibroblasts close to cancer cells, which perturbs the microenvironment through paracrine signaling." (PMID 32414408, 2020). "This indicates that low ATR levels in cancer and/or stromal fibroblasts in these tumors can significantly predict high risk of recurrence." (PMID 32414408, 2020). "Next, we sought to investigate the predictive value of ATR expression levels in cancer cells as well as in stromal fibroblasts as a candidate biomarker for clinical outcome of patients with LABC." (PMID 32414408, 2020). "Inhibition of the kinase ATR, a central regulator of the DNA damage response, eliminates subsets of cancer cells in certain tumors." (PMID 33144657, 2020). "Here we discuss the experimental evidences supporting this mode of action and their implications in the design and use of specific kinase inhibitors for ATM, ATR and DNA-PKcs for cancer therapy." (PMID 32015826, 2020). "Cancer cells rely on the ATR replication stress response pathway to ensure DNA replication and continued cellular proliferation." (PMID 33137164, 2020).
cancer (continued). "This suggests the use of ISR inhibitors with nucleoside analogs and/or ATR inhibitors in an attempt to achieve synergistic responses to eliminate cancer cells." (PMID 32678076, 2020). "Along this idea, it is interesting to note that our experiments indicate that ATR depletion impairs three-dimensional (3D) invasion and lung homing of cancer cells." (PMID 32973141, 2020). "Univariate Cox regression analysis confirmed that low ATR levels in both stromal fibroblasts and cancer cells were a significant indicator of poor clinical outcome." (PMID 32414408, 2020). "Cancer cells with significant A3A activity rely on DNA repair pathways and the ATR checkpoint to tolerate A3A-induced replication stress and genomic instability." (PMID 32532990, 2020). "By utilizing the natural balance that exists in normal human cells between cis- and trans-ATR isoforms, we propose cis-ATR as a novel, potential target in cancer treatment." (PMID 32426354, 2020). "ARID1A loss-of-function mutations sensitize cancer cells towards inhibition of EZH2, ATR, PARP, HDAC6, and HSP90 (and others)." (PMID 32272809, 2020). "Here, we report that intrinsic ATR signaling has a pivotal role in sustaining DNA end resection capacity in cancer cells and that ATR inhibition can be exploited as a strategy to potently modulate DNA end resection." (PMID 32743550, 2020). "Cancer cells rapidly proliferate and thereforetend to undergo much replication stress and thus are particularlydependent on ATR." (PMID 33135887, 2020). "Identification of the phosphatases which have activities at Ser428 is particularly important to cancer treatment as dephosphorylation of this residue leads to an increase of anti-apoptotic cis-ATR formation and poor prognosis for cancer treatment." (PMID 32426354, 2020). "In the future, it will be essential to transfer the knowledge accumulated about the effect of long-term ATR inhibition to more complex systems such as tumor organoids and, more importantly, to mouse models of human cancers." (PMID 32743550, 2020). "In 7 out of 10 cases, the level of ATR in stromal fibroblasts was matching the level of ATR in the corresponding cancer cells." (PMID 32414408, 2020). "Due to increased amount of replication stress, cancer cells heavily rely on ATR to complete DNA replication and cell cycle progression." (PMID 33137164, 2020). "Overall, our findings reveal a key pro-resection function for ATR and define how ATRi can be used for effective manipulation of DNA end resection capacity and DNA repair outcomes in cancer cells." (PMID 32743550, 2020). "ATR inhibitors, in combination with chemo- and radio-therapy, have been utilized in a synthetic lethality approach to sensitize cancer cells for cell death with varied results." (PMID 32426354, 2020). "A total of 103 breast pretreatment tumor tissues were assessed for ATR expression in both cancer as well as stromal cells." (PMID 32414408, 2020). "A recent study has suggested that ATR inhibitors are selectively active in cancer cells that employ the alternative lengthening telomere (ALT) pathway." (PMID 32366852, 2020). "For example, ATR inhibition has been shown to sensitize PARP inhibitor‐resistant BRCA1 mutant cancer cells to PARP inhibition through blocking protection of stalled replication forks." (PMID 31529615, 2019). "Altogether, these data indicate that cancer cells adapt to RS by overexpressing Claspin and Timeless, independently of ATR signaling." (PMID 30796221, 2019). "Inhibitors of other potential DDR targets including PARP, CHK1/2, WEE1, and DNA-PKcs are considered as novel therapeutic approach for development of ATM and ATR inhibitors with the potential to improve cancer outcome." (PMID 30975222, 2019).
cancer (continued). "While the ATR/CHK1 pathway is often inactivated by mutations, CHK1 itself is rarely mutated in human cancers." (PMID 30428154, 2019). "The ATR-Chk1 axis is a promising therapeutic target in cancer, and ROS dependent mechanisms that lead to ATR-Chk1 inhibitor resistance are worthy of further investigation." (PMID 30612957, 2019). "ATR inhibition further increased the numbers of cGAS‐positive micronuclei and the extent of cytokine production in olaparib‐treated BRCA2‐deficient cancer cells." (PMID 31529615, 2019). "Many studies have shown dysregulation of the components of the ATR-Claspin-Chk1 pathway in different cancers." (PMID 31362447, 2019). "BAY1895344 is an ATR inhibitor developed by Bayer that is used to inhibit the proliferation of human cancer cell lines with a median IC50 of 78 nM." (PMID 31018854, 2019). "Altogether, we show that ATR inhibition induces premature mitotic entry and mediates synergistic cytotoxicity with PARP inhibition in HR‐deficient cancer cells, which involves enhanced genomic instability and inflammatory signaling." (PMID 31529615, 2019). "Inhibition of ATR in cancer cells has been shown to generate excessive ssDNA at stalled replication forks which exhausts cellular RPA and leads to mitotic catastrophe." (PMID 30863489, 2019). "Cell death induction of cancer cells treated with increasing combinations of replication and kinase (ATR and Chk1) inhibitory drugs was proportional to the appearance of pan-nuclear γ-H2AX pattern." (PMID 30871194, 2019). "Previous studies, including our own, have demonstrated synergism between G2/M DNA damage checkpoints inhibitors (WEE1, Chk1 or ATR) and PARPi in several cancer models." (PMID 31191824, 2019). "Emerging preclinical evidence indicates that ATR inhibitors can block the programmed death-ligand 1 upregulation on cancer cell surfaces and mitigate the tumor infiltration of regulatory T cells after treatment with radiation or cisplatin." (PMID 31018854, 2019). "Collectively, these preclinical studies provide the rationale for using an ATR inhibitor/PARP inhibitor combination in HR-proficient and HR-deficient cancer cells." (PMID 31018854, 2019). "DNA repair‐targeting therapies, such as ATR and CHK1 inhibitors (which are most effective against cancers carrying ATM mutations), can be used in combination with current genotoxic chemotherapies in CRCs to further improve therapy response." (PMID 30714316, 2019). "We started the present study by assessing the ATR expression level in 12 human breast CAFs and their counterpart fibroblasts isolated from histologically normal adjacent cancer-free tissues (TCFs)." (PMID 30410668, 2018). "Among these receptors, ATR represents a central cellular response regulator that is activated under replication stress and was proposed to be a therapeutic target in cancer therapy." (PMID 30020984, 2018). "Impaired DNA-damage responses and increased replication stress are often associated with tumourigenesis, and, at the same time, the higher level of DNA damage also makes cancer cells more reliant on ATR-dependent stress responses than normal cells are." (PMID 29720710, 2018). "Pharmaceutical development of ATR inhibitors for cancer therapy is an attractive anti-cancer strategy." (PMID 29396668, 2018). "Our results showed that expression of ATR and Chk1 were significantly increased in cancer tissues, as show the mRNA and protein levels." (PMID 29870526, 2018). "If the activation of ATR in DNA2 null cells is to overcome endogenous replicative stresses at the centromeric DNA region as previously suggested, targeting both DNA2 and ATR will generate synergy in cancer treatment." (PMID 29773570, 2018).